STAT1 (signal transducer and activator of transcription 1)
Diseases named in the same sentence as STAT1 in open-access papers (continued):
Sharing a sentence is not in itself a finding about the gene and the disease.
breast tumors (continued). "It has been published that STAT1 binds to Csf1 promoter in tumor cells; by this way STAT1 could regulate breast tumor-derived CSF-1 production which drives to the recruitment, in situ proliferation, and M2 phenotype of CD11blow F4/80high TAMs." (PMID 28197019, 2017). "Finally, the ability of diminished tyrosine kinase signalling to initiate STAT1-driven immune surveillance can be overcome by compensatory STAT3 hyperactivation in breast tumours." (PMID 28276425, 2017). "Furthermore, JAK2-STAT3 activation was shown to confer ovarian hormone independency in mice with established STAT1−/− breast tumors undergoing OVX." (PMID 27391074, 2016). "Therefore, modulating STAT1 - a master regulator of collective immunoregulatory factors, using STAT1 inhibitor in MCT-primed breast tumor effectively shifted the immune homeostasis in the favor of immunogenicity, which resulted in a much improved response to ICB." (PMID 37055410, 2023). "Generally, STAT1 and STAT3 are highly expressed and considered to be among the most important transcription factors in human breast tumors." (PMID 33922837, 2021). "MT/ShcA+/+ cells model breast tumours that possess an activated tyrosine kinase/ShcA axis, which simultaneously activates STAT3 and represses STAT1 to establish immune suppression." (PMID 28276425, 2017). "Taken together, the results of the present study would suggest an important role for STAT1 and STAT3 in regulating anti-tumour immunity in the breast tumour microenvironment." (PMID 27769057, 2016). "Mice lacking STAT1 developed ER+ breast tumours with a long latency (~23 months)." (PMID 36982737, 2023). "They further suggest that the STAT1/STAT3 ratio is dynamically regulated in individual human breast tumours and support the potential for utilizing this ratio to predict intrinsic immune surveillance and sensitivity of breast tumours to specific immunotherapies." (PMID 28276425, 2017). "In the absence of STAT1, the negative control on STAT3 signaling is absent, favoring the development of breast tumors." (PMID 41463071, 2025).
head and neck squamous cell carcinoma (27 papers, 2016 to 2025). A squamous cell carcinoma that arises from any of the following anatomic sites: lip and oral cavity, nasal cavity, paranasal sinuses, pharynx, larynx, and salivary glands. "Other studies have found that STAT1 has an antitumor effect, as it can inhibit T-cell exhaustion and myeloid-derived suppressor cell accumulation in head and neck squamous cell carcinoma." (PMID 36593458, 2023). "A more recent study stated that the tumor growth and metastasis of head and neck squamous cell carcinoma were much faster in Stat1–/– mice than in Stat1+/+ mice." (PMID 38304256, 2023). "In head and neck squamous cell carcinoma, miR-375 acted as a modulator to increase the cellular immune response to cancer by inhibiting PD-1/PD-L1 signaling via the Janus kinase 2/signal transducer and activator of transcription 1 pathway." (PMID 33535558, 2021). "The activation of IFNAR1/STAT1 signaling in head and neck squamous cell carcinoma (HNSCC) by IFN-α is associated with the establishment of an immunosuppressive microenvironment favoring the expression of PD-L1 in HNSCC cells, PD-1 in immune cells and impairs the lithic activity of NK cells." (PMID 34571790, 2021). "A recent study showed that tumor growth and metastasis of head and neck squamous cell carcinoma were promoted in STAT1−/− mice than in STAT1+/+ mice, suggesting that STAT1 may be an essential antitumor factor." (PMID 34572789, 2021). "Furthermore, it mediates cisplatin-resistance for head and neck squamous cell carcinoma via STAT1/3 pathways." (PMID 33928101, 2021). "Furthermore, a connection between increased STAT1 expression and radio-resistant tumor cells was reported in head and neck squamous cell carcinoma." (PMID 34638338, 2021). "Similar results were demonstrated in head and neck squamous cell carcinoma (HNSCC), where STAT1−/−-mice showed more metastasis than STAT1+/+-mice." (PMID 34638338, 2021). "In head-neck squamous cell carcinoma (HNSCC), STAT1, and STAT2 expression levels were significantly upregulated in tumors compared to normal tissues and positively correlated with individual cancer stage, grade, and nodal metastasis." (PMID 38191598, 2024). "So far, little is known about CDK19’s role in head and neck squamous cell carcinoma (HNSCC) progression, its link to STAT1 activity, and related immune modulation." (PMID 32752128, 2020). "For example, STAT1 and STAT5A genes are silenced by DNA methylation in squamous cell carcinoma of the head and neck (SCCHN) and NPM1-ALK–expressing lymphomas, respectively." (PMID 31530290, 2019). "In head and neck squamous cell carcinoma (HNSCC) and triple-negative breast cancer (TNBC), type III collagen stimulates DDR1 phosphorylation, activating STAT1 to maintain tumor dormancy." (PMID 40563472, 2025). "In melanomas, renal cell carcinomas (RCC) and squamous cell carcinomas of the head and neck (SCCHN), phosphorylated STAT1, and not STAT3, is involved in IFNγ-triggered PD-L1 transcription." (PMID 35402280, 2022).
Hepatitis (27 papers, 2011 to 2026). Inflammation of the liver. "The synthesis and activation of STAT1 are increased in the liver of ConA-induced hepatitis mice, and STAT1-deficient mice attenuate ConA-induced liver damage." (PMID 30647537, 2018). "Selective hepatocyte depletion of SOCS1 in liver-specific SOCS1 knockout mice resulted in enhanced concanavalin A-induced hepatitis associated with pro-apoptotic signals (including STAT1 and JNK)." (PMID 26891124, 2016). "Overall, our analysis suggests that type I and II IFN-induced activation of STAT1 is driving the expansion of inflammatory transitioning monocytes during TLR9-induced liver inflammation." (PMID 41561071, 2026). "In summary, we show that type I and II IFN-induced STAT1 activation drives TLR9-associated features, particularly liver inflammation, which is characterized by IFN-γ-producing cycling T cells, cDC2s, and monocytes transitioning into inflammatory Mφs." (PMID 41561071, 2026). "In a model of concanavalin A-induced hepatitis, activated STAT1 exacerbates its induction of hepatitis, whereas activated STAT3 attenuated hepatitis." (PMID 36671504, 2023). "Hepatitis, haemophagocytic lymphohistiocytosis (HLH), and disseminated intravascular coagulation are severe complications of AR STAT1 deficiency." (PMID 36339330, 2022). "IFN‐γ was demonstrated to upregulate the expression of many autophagy‐related proteins such as double‐stranded RNA‐dependent protein kinase (Pkr), Atg7, LC3‐II, p62 through the Janus Kinase 1(JAK1)/STAT1 signaling pathway in Con A‐induced hepatitis." (PMID 35263512, 2022). "NF‐κB2 levels followed a similar pattern in infants with liver inflammation (r = 0.4522), while Stat1 expression was reduced and correlated negatively with Prc expression (r = −0.4906)." (PMID 32821877, 2020). "It was concluded that ARC alleviated cell autophagy and apoptosis via the inhibition of IFN-γ/IL-6/Stat1 signaling in ConA-induced hepatitis." (PMID 30177931, 2018). "Disruption of the IFN-γ or STAT1 genes abolished elevated ALT activities and necrosis, suggesting that IFN-γ/STAT1 plays an essential role in ConA-induced hepatitis." (PMID 28377718, 2017). "The transcription factor STAT1, which is associated with the IFN-γ signaling pathway, is crucial for ConA-induced hepatitis." (PMID 28377718, 2017). "STAT3 may inhibit inflammation by inhibiting STAT1, so STAT3 can inhibit the activation of the pro-inflammatory factor STAT1 in ConA-induced and LPS-induced hepatitis." (PMID 36761734, 2023). "Therefore, we investigated the effect of Sophocarpine on the activation of STAT1 and the expression of T-bet in ConA-induced hepatitis." (PMID 28377718, 2017). "In addition, berberine decreased the production of TNF‐α, IFN‐γ, IL‐2, IL‐1β, increased the level of IL‐10 and alleviated hepatitis by blocking the transcriptional activity of signal transducer and activator of transcription 1 (STAT1), which was largely dependent on activating AMPK." (PMID 35263512, 2022). "These cell populations exhibit elevated STAT1 expression and type I and II interferon (IFN) signatures, resembling immune profiles of patients with cytokine storm syndromes and liver inflammation." (PMID 41561071, 2026). "The activation of STAT1 (pSTAT1) and STAT3 (pSTAT3) plays a pivotal role in controlling liver steatosis and liver inflammation." (PMID 34112940, 2021). "It has been reported that AG protects against drug-induced hepatitis by suppressing the immune system and regulating autophagy by inhibiting the IFN-γ/IL-6/Stat1 and IL-6/Bnip3 pathways in mice." (PMID 31163644, 2019). "Further, the mRNA level of Stat1 was decreased by ARC pretreatment, thus suggesting that ARC attenuated the cell apoptosis and autophagy in ConA-induced hepatitis by suppressing the synthesis and activation of Stat1." (PMID 30177931, 2018).
Hepatitis (continued). "STAT-1 is activated in response to IFN-γ in concanavalin-A induced hepatitis and the lipopolysaccharide/d-galactosamine-induced hepatitis model and plays a harmful role in these models of hepatotoxicity." (PMID 23935693, 2013). "IFN-γ activates STAT1, which initiates inflammatory signals in APAP-induced hepatitis by the induction of multiple cytokines, chemokines, adhesion molecules, and Fas/FasL." (PMID 23935693, 2013). "MLKL is known to regulate necroptosis during hepatitis through signal transducer and activator of transcription 1 rather than via RIPK3." (PMID 37828052, 2023). "Further, we also observed that WT→Ifnar1−/− and WT→Stat1−/− bone marrow chimeric mice were protected from early hepatitis upon LCMV infection, suggesting that the liver damage is mediated by nonhematopoietic IFNAR1-STAT1 signaling." (PMID 26588782, 2015).
lymphoma (27 papers, 2002 to 2025). A malignant (clonal) proliferation of B- lymphocytes or T- lymphocytes which involves the lymph nodes, bone marrow and/or extranodal sites. "We find that MYC-driven human lymphomas are associated with concomitant suppression of STAT1/2 and NK exclusion." (PMID 32503978, 2020). "Similar results were obtained with STAT1-deficient lymphoma cells (line 9PC, 9OVA)." (PMID 22479645, 2012). "Pentose phosphate pathway inhibitors enhance macrophage phagocytosis of lymphoma cells by suppressing the UDPG/STAT1/IRG1/itaconate axis." (PMID 41459510, 2025). "Among IEI-associated genes,7,9NFKB2,26PIK3CD, STAT1,27PALB2, SH2D1A,28TNFRSF13B,10MSH6, CTLA4 genes had previously been reported in lymphoma or hematological malignancies genomic studies or are lymphoma susceptibility genes." (PMID 38547930, 2024). "In summary, miR130b enhanced B-lymphoma cell sensitivity to OX40 agonistic antibody and LNPs miR130b antagomir through modulating OX40/OX40L-mediated lymphoma cell interaction with Th17 cells via IFNAR1/p-STAT1 axis." (PMID 35301282, 2022). "Collectively, our findings suggest a common paradigm of NK suppression in both human and mouse MYC-driven lymphomas, which occurs in part due to the direct repression of the STAT1/2-Type I IFN signaling cascade by the MYC oncogene." (PMID 32503978, 2020). "We show that MYC-driven lymphomas evade NK surveillance by transcriptionally repressing the STAT1/2-Type I IFN signaling required for NK cell maturation." (PMID 32503978, 2020). "Lymphoma-intrinsic MYC arrests NK maturation by transcriptionally repressing STAT1/2 and secretion of Type I Interferons (IFNs)." (PMID 32503978, 2020). "Our findings suggested that lymphoma-intrinsic MYC represses STAT1/2-Type I IFN signaling; thereby blocking the maturation of NK cells in the tumor microenvironment." (PMID 32503978, 2020). "We examined MYC-driven human lymphoma patients for evidence of repression of STAT1/2 signaling and NK cell-mediated immune surveillance." (PMID 32503978, 2020). "In contrast to wild-type recipients, 80–100% of STAT1-, IFN-γ-, or IFN-γ receptor-deficient recipients died of lymphoma, indicating that host IFN-γ signaling is critical for rejection." (PMID 22479645, 2012). "A STAT1-deficient cell line (9PC) established from a spontaneous lymphoma was retrovirally transduced with OVA-IRES-GFP (9OVA) and injected into either wild-type or STAT1-deficient recipients." (PMID 22479645, 2012). "Next, we investigated whether modulation of MYC in vitro in MYC-driven B- and T- lymphoma cell lines differentially regulates STAT1/2-Type I IFN signaling." (PMID 32503978, 2020). "Tumor-intrinsic signaling changes post MYC inactivation in our T-lymphoma line derived from SRα-tTA/tet-O-MYC mice mirrored those observed in the human BL-like model with MYC inactivation leading to activation of STAT1/2-Type I IFN signaling." (PMID 32503978, 2020). "In human T lymphoma cells or mouse cells, loss of STAT3 leads to prolonged activation of STAT1." (PMID 30355451, 2018). "DNA hypermethylation of SOCS1 is also frequently found in certain types of lymphomas and in myelodysplastic syndrome, which may result in enhanced STAT1 and Jak2 activity and hence cell proliferation." (PMID 28445952, 2017). "Notably, tumors arising in IFN-γ−/− and IFN-γR−/− mice were invariably GFP-negative, whereas all lymphomas arising in STAT1−/− mice were GFP-positive." (PMID 22479645, 2012). "Quantification of data confirmed elevated levels of tyrosine phosphorylation of both STAT1 and STAT3 and reduced levels of both NF-κB and IκBα in lymphoma cells from mice expressing STAT1-∆N." (PMID 40287766, 2025).
lymphoma (continued). "The results of the Western blot analysis comparing normal lymph nodes to B cell lymphoma nodes indicated that STAT1 and JUND are significantly overexpressed in lymphomas." (PMID 39518046, 2024). "Whereas NDV infected different lymphoma subtypes with variable efficiency, it induced robust expression of IFN-stimulated genes (STAT1, MX1, ISG15) across all patient samples." (PMID 36418317, 2022). "We observed a significant suppression of STAT1 and STAT2 levels, and a reduction in total and activated NK cell subsets in T-lymphoma patients in comparison to their normal counterparts." (PMID 32503978, 2020). "Concordant with a previous study where MYC was shown to transcriptionally repress STAT145, we found that MYC binds the STAT1 promoter in P493-6 human BL and mouse MYC-driven T-lymphoma." (PMID 32503978, 2020). "Hence, suppression of STAT1/2-Type I IFN signaling is a signature of both T- and B- MYC-driven lymphomas." (PMID 32503978, 2020). "Next, we compared transcript levels of STAT1, STAT2 and other Type I IFN signaling components in normal B cells (MYCLOW), pre-lymphoma B cells from Eμ-MYC mice (MYCHIGH), and overt B-cell lymphoma from Eμ-MYC mice (MYCHIGH), a mouse model of MYC-driven B-lymphoma (GSE5101140)." (PMID 32503978, 2020). "The overproduction of EIF4E2 AAb in lymphoma patients may inhibit the downstream translation of oncogenic proteins like VEGF, MYC, cyclins, and STAT1." (PMID 32483460, 2020). "Lymphomas in this model lacking Tyk2 have reduced STAT1 and STAT3 phosphorylation and reduced expression of Mcl1, a pro-survival member of the BCL2 family." (PMID 30131584, 2019). "Lymphomas arising in STAT1−/− mice invariably expressed GFP consistent with the lack of T cell immigration to the tumor site." (PMID 22479645, 2012). "In addition to increased activity of the IL-27R/STAT1/T-bet axis in FcRL4+ B cells, observed in the current study, others have shown that expression levels of IFN-γ and type-II IFN inducible genes were increased in minor salivary gland tissue of SS patients with versus without lymphoma." (PMID 32201227, 2020).
fungal infections (26 papers, 2012 to 2025). "AD gain of STAT1 activity predisposes patients to invasive fungal infections, including coccidioidomycosis." (PMID 41607488, 2025). "Due to the children patient's repeated superficial fungal infections, as well as autoimmune and endocrine diseases, we considered the STAT1 mutation as the pathogenic mutation, which was the reason for the patient's CMC related manifestations." (PMID 40625894, 2024). "Subjects affected by Signal Transducer and Activator of Transcription 1 (STAT1) deficiency suffer from life-threatening bacterial, mycobacterial, viral, and fungal infections." (PMID 31396241, 2019). "Of interest, patients with loss-of-function STAT3 mutations or with gain-of-function STAT1 mutations show similar susceptibility to fungal infections." (PMID 31998303, 2019). "Since curative treatment is still unavailable, most of the patients with STAT1 GOF mutations receive prolonged systemic antimicrobial medications to control clinical symptoms of recurrent fungal infections and other infections." (PMID 28348565, 2017). "Chronic and/or recurrent mucocutaneous fungal infections with predominantly C. albicans are the major infectious complications in patients with STAT1 GOF mutations and generally arise in infancy or childhood." (PMID 28348565, 2017). "This phenotype was recapitulated in neutrophils deficient for STAT1 suggesting that, during fungal infections, IFN-λ-dependent STAT1 activation mediates a transcriptional program that protects the host." (PMID 29234323, 2017). "All STAT1 mutations, so far reported in patients with systemic or local fungal infections, are located in either the coiled-coil domain or the DNA-binding domain, which both constitute the interface surface for the antiparallel dimer configuration." (PMID 23922848, 2013). "On the one hand, severe fungal infections are associated with monogenic primary immunodeficiencies such as defects in STAT1, STAT3 or CARD9, recently discovered as novel clinical entities." (PMID 23629947, 2013). "Therefore, further investigations are necessary to elucidate the immune responses to fungal infections associated with STAT1." (PMID 41607488, 2025). "On the other hand, impaired Th17 response in GOF STAT1 defect and AD hyper-IgE syndrome leads to CMC and invasive fungal infections caused by filamentous and dimorphic fungal pathogens." (PMID 31572394, 2019). "A loss of function of STAT1 leads to increased susceptibility to mycobacterial disease, whereas a GOF mutation leads to CMC and invasive endemic fungal infection." (PMID 26845151, 2016). "However, even in cases with an intact IL-17 response, the local effects of an IFN-γ/STAT1–driven interferonopathy alone can be enough to promote mucocutaneous fungal infections by impairing the integrity of the epithelial barrier." (PMID 39114664, 2024). "Thus, rational use of JAK inhibitors must be considered when treating STAT1 GOF or STAT3 GOF patients, in which the risk for viral and fungal infections or cancer is already elevated, respectively, in those patients." (PMID 37140667, 2023). "However, the negative regulatory role of RGS1 stimulated by STAT1 during the immune response against fungal infection remains to be further studied." (PMID 36225936, 2022). "While early, translation independent, regulation of neutrophil function by IFN-λ suppresses ROS production and degranulation in response to inflammatory stimuli, during fungal infections, STAT1-dependent action is critical for the activation of neutrophil functions in vivo." (PMID 29234323, 2017). "Notably, SNPs in STAT1, a key mediator of both IFN-I and IFN-II (IFN-γ) signaling, are implicated in the outcome of invasive fungal infections in humans." (PMID 22911155, 2012). "Because, in STAT1 GOF–mutated individuals, both these immune signaling alterations usually concur, their effects may jointly contribute to their heightened susceptibility and the severity of fungal infections." (PMID 39114664, 2024).